SMAD4 (SMAD family member 4)
Diseases named in the same sentence as SMAD4 in open-access papers (continued):
Sharing a sentence is not in itself a finding about the gene and the disease.
cancer (continued). "Presumably, SMAD4 mutations had occurred in the primary polyps, and some of these mutated cells then developed into carcinoma." (PMID 35154600, 2021). "SMAD4 was the only gene with cancer-specific mutations in more than one case, highlighting the potentially unique role this gene plays in pancreatic carcinogenesis." (PMID 32796935, 2020). "SMAD4 deficiency can enhance the glycolytic capacity of cancer cells with upregulation of glucose transporter expression contributing to aerobic glycolysis, which is the main metabolic pathway in PDAC." (PMID 32429474, 2020). "This role has been previously suggested by next generation sequencing of high-grade PanINs showing an absence of SMAD4 mutations in precancerous lesions, as well as cancer-specific SMAD4 mutations reported in a paired PanIN/carcinoma analyses." (PMID 32796935, 2020). "Smad4 is a gene implicated in several cancers, including EC, albeit its role in endometrial carcinogenesis is yet not clear." (PMID 31293968, 2019). "SMAD4 mutations have also been observed in cancers with mucinous differentiation, especially those of high grade." (PMID 30730996, 2019). "It is undoubtedly that SMAD4 loss causes the insensitivity of cancer cells to the anti-mitogenic activity of TGFβ, and then abrogating RB-mediated E2F1 suppression." (PMID 31569425, 2019). "Chemoresistance is also an important property of malignant phenotype of cancer cells, and loss of SMAD4 is a predictive biomarker for 5-FU-based chemotherapy." (PMID 31756952, 2019). "An exploratory analysis between CNV in RD samples and DFS revealed cancers bearing a copy gain of a region near SMAD4 on chromosome 18q were associated with poor prognosis, likely through upregulation of SMAD2." (PMID 31383035, 2019). "In general, 2.5 to 4% of the HNSCC tumors demonstrate the somatic mutation of SMAD4, making SMAD4 the fourth mutated gene in different types of cancers." (PMID 31867281, 2019). "As a result, miR-34a overexpression was found to significantly inhibit BM, whereas Smad4 overexpression significantly accelerated the invasion of cancer cells into the bone and caused more severe bone damage." (PMID 31349837, 2019). "Luciferase activity assay showed that miR-34a-5p directly target Smad family member 4 (Smad4), which is associated with cancer cell invasiveness and metastasis." (PMID 30617054, 2019). "The activin signaling causes growth inhibition and apoptosis principally through SMAD4-dependent pathways in numerous cancers." (PMID 31480737, 2019). "Cancer hallmark enrichment and pathway analysis suggested that the upregulation of cell cycle-related genes in SMAD4-deleted PDAC." (PMID 31569425, 2019). "Mechanistically, UA62784 preferentially activates CDK1 and induces cell cycle arrest and apoptosis in cancer cells with deficient SMAD4." (PMID 31569425, 2019). "Varying rates of SMAD4 mutations have been detected in a wide range of cancers by large-scale exome sequencing." (PMID 31867281, 2019). "SMAD4 presented loss of 25% (21/95) in normal pancreatic tissues and 75.7% (71/95) in carcinoma tissues." (PMID 31684910, 2019). "We also observed a high frequency of chromosomal losses in two other significantly mutated known cancer genes: SMAD4 (n = 46) and SOX9 (n = 44)." (PMID 29522538, 2018). "Comprehensive mining of published in vitro data revealed that simultaneous mutations in KRAS and SMAD4 are associated with cancer cell radioresistance." (PMID 30220971, 2018).
cancer (continued). "Cancer-associated SMAD2 mutations are also defective for SMAD2/SMAD4 complex formation, and cutaneous papillomavirus E6 proteins seem to functionally mimic SMAD2 mutations." (PMID 28107544, 2017). "In previous results, we revealed that activation of PAK1 in Smad4 deficient cancers suppresses PUMA-mediated apoptosis." (PMID 28423593, 2017). "Mutations or alterations of the SMAD4 gene, which maps to chromosome 18q, have been observed for several cancer types, including colon, lung and pancreas." (PMID 28340489, 2017). "The deletion of the SMAD4 gene or the abolishment of the protein function via somatic mutations leads to cancer through the breaking of a negative regulatory pathway." (PMID 27150584, 2016). "For example, Smad4 gene mutations have been identified in most pancreatic and colorectal cancers, and in a lesser proportion in other cancers, such as hepatocellular, ovarian, intestinal, and lung carcinomas." (PMID 27827889, 2016). "The expression of S100A8/A9 is also intimately linked with SMAD4 status: it is prevalent in stromal cells when cancer cells express SMAD4, whereas in SMAD4 homozygous deletion cancer cells independently acquire the ability to express S100A8/A9." (PMID 27655713, 2016). "Immunohistochemical analysis showed SMAD4 nuclear loss in 10 of 30 EBV-positive cancer patients, of whom five (50% of SMAD4 loss/EBV-positive) died." (PMID 27438138, 2016). "In particular, SKI and PRKCZ in 1p36.33 have been reported to contribute to the loss function of TGFBR2 and SMAD4 in cancer." (PMID 26374103, 2015). "With an important role in maintaining anoikis, Smad4 is often defective in cancer by means of mutation or deletion." (PMID 26587543, 2015). "We used hazard ratios (HRs) with 95% confidence interval (CIs) as the effect estimation to evaluate the association of Smad4 with overall survival (OS), cancer-specific survival (CSS) or recurrence-free survival (RFS)." (PMID 25333693, 2014). "In summary, this study demonstrated that loss of Smad4 staining was a poor predictor for survival in patients with various cancers." (PMID 25333693, 2014). "In our study, loss of Smad4 staining expression was associated with unfavorable outcomes for various cancers, a finding that was consistent with the results of previous studies." (PMID 25333693, 2014). "S100A8/A9, NT-S100A8 are overexpressed in PDAC stroma when cancer cells express Smad4, suggesting that they are linked with TGFβ1 signalling." (PMID 24670043, 2014). "The human locus 18q21, which encodes the SMAD2 and SMAD4 genes, is often mutated or lost completely in several cancers." (PMID 24886203, 2014). "Reports of SMAD4 expression in prostate and other cancers are complex and variable, although mutation of the SMAD4 gene appears rare during PCa progression." (PMID 24708576, 2014). "Smad4 plays an important role in human physiology, and its mutations were found with high frequency in a wide range of human cancers." (PMID 23591524, 2013). "We noted that most studies investigated established cancers and often found the loss of SMAD4 gene occurring at later stages of tumorigenesis." (PMID 23826135, 2013). "Genetically, Smad2 and Smad4 are frequently mutated or deleted in certain human cancers whereas Smad3 mutation or deletion is infrequent." (PMID 22204491, 2011). "Gene deletion and mutation of Smad4 and Smad2 have been identified in certain human cancers and implicated in cancer development." (PMID 22204491, 2011). "SMAD4 somatic mutations were clustered in the MH2 domain supporting the observation that the MH2 domain is a mutation hotspot in many cancer types." (PMID 21835029, 2011).
cancer (continued). "However, in cancer, the loss or downregulation of SMAD4 can disrupt these processes, leading to uncontrolled cell proliferation." (PMID 40224178, 2025). "Loss of function by mutations in SMAD4 contributes to the development of various types of cancers." (PMID 39727835, 2024). "Research has demonstrated that mutations or decreased expression of Smad4 correlate with advanced disease stages, lymph node metastasis, and reduced survival rates in cancer patients, highlighting its potential as a target for therapeutic intervention and prognostic assessment in oncology." (PMID 39596873, 2024). "However, the development of intrinsic radioresistance in SMAD4-deficient PDAC patients inevitably leads to cancer relapse and a poor prognosis." (PMID 39528473, 2024). "Interestingly, SMAD4 is frequently mutated in cancers, resulting in the promotion of invasion and metastasis." (PMID 39335144, 2024). "Among these, the SMAD4 c.424+5G>A variant, which we molecularly characterized in the present study, was mostly identified in patients with a personal and/or family history of cancer." (PMID 39063183, 2024). "The mutation and dysregulation of the SMAD4 gene are widely present in various cancers, sparking research interest in whether this gene also plays a crucial role in CRC." (PMID 39164192, 2024). "Combination therapies targeting activated BRK signalling may therefore have a synergistic effect in the treatment of SMAD4-deficient cancers." (PMID 37685308, 2023). "Four genes, RAB10, KLF5, TCF7L2, and CTNNB1 had gene essentiality strongly correlated with both SMAD4 mutation and SMAD4 CNA in various cancer cells (i.e., genes that are more essential when SMAD4 copy number is decreased or when SMAD4 is mutated, P values inferior to 1E-04)." (PMID 37377893, 2023). "SMAD4-deficient GC cells exhibited the expansion of CD133+ cancer stem cells, along with the inhibition of dendritic cell (DC) differentiation and the aggregation of cytotoxic T cells with granulocyte myeloid-derived suppressor cells (G-MDSC) via CXCL1-containing secretomes." (PMID 37685308, 2023). "Indeed, previous work that linked SMAD4 polyubiquitination with its proteasomal degradation was largely done in cancer cell lines including with use of some cancer associated SMAD4 mutants." (PMID 37863914, 2023). "In conclusion, SMAD4 deficiency was associated with poorer clinical prognosis, chemoresistance, and reduced immune infiltration, supporting its use as a prognostic marker in cancer patients." (PMID 37685308, 2023). "Almost 30% of serrated cancer patients have an oncogenic driver mutation in SMAD4/TGFβ pathway." (PMID 38136364, 2023). "For example, SMAD4 mutations expanded during metastasis in GB-A1 and GB-S3 and have been associated with distant metastasis and poor prognosis in various cancers, including GBAC." (PMID 36476508, 2022). "In addition, cancer-related mutations were found in P in 18 genes, including SMAD4 (11.9%), PIK3CA (11.9%), FBXW7 (9.5%), PTEN (7.1%), and BRAF (7.1%)." (PMID 35892888, 2022).
cancer (continued). "SMAD4 loss has been shown to promote chemoresistance in multiple cancer types, including CRC." (PMID 35805024, 2022). "Additionally, we calculated the frequencies of genes in the three phenotypes, which were reported to be associated with the invasion and progression of cancer, such as SMAD4, APC, and ERBB4." (PMID 35401671, 2022). "We anticipate that specific targeting of BMP2/4 using the VHHs could form a basis for personalised treatment in SMAD4 deficient EAC, and perhaps in other SMAD4 mutated cancers." (PMID 35902550, 2022). "(j, k) Cancer missense mutations in the MH2 domain of Smad4 can compromise Arl15-Smad4 interaction." (PMID 35834310, 2022). "Thus, we conducted a meta-analysis of eligible studies to investigate an association between the loss of SMAD4 expression and the resistance of cancer to chemotherapy in order to clarify the exact prognostic value of SMAD4 loss in drug resistance." (PMID 34048444, 2021). "By contrast, SMAD4 mutations are rarely observed in other cancer types." (PMID 34070531, 2021). "The result indicated SMAD4 expression loss resulted in the cancers drug-resistance significantly." (PMID 34048444, 2021). "Although there were reports that analyzed the correlation of the SMAD4 expression loss with poorer cancer prognosis, it was still unclear whether SMAD4 expression loss was significantly related to drug resistance or not." (PMID 34048444, 2021). "Clinically, SMAD4 has been linked with metastasis in a number of cancers 31, 32, 34-37." (PMID 33746597, 2021). "Patients with SMAD4 gene inactivation might be spared the risk of surgery because their cancer is more likely to metastasize, whereas patients with intact SMAD4 may benefit from the local control provided by neoadjuvant therapy and surgical resection." (PMID 33867818, 2021). "Smad4 inactivation is associated with different types of cancer." (PMID 34381046, 2021). "To date, Smad4 is known as the most common Smad family gene mutated in cancer." (PMID 34760883, 2021). "There are also several systematic reviews that studied the clinicopathological significance of SMAD4 loss in various cancers, which had revealed that loss of SMAD4 was indeed associated with poorer survival and hence, is a negative prognostic indicator in patients." (PMID 34048444, 2021). "The pro-tumorigenic effect of TGFβ in Smad4-deficient cancers remains incompletely understood, but the loss of Smad4 may allow cancer cells to escape TGFβ-mediated growth arrest and immune surveillance." (PMID 33990575, 2021). "Mutation and promoter hypermethylation of SMAD4 has been reported in numerous human cancers." (PMID 33825073, 2021). "In conclusion, activins and follistatin are pathologically altered in CRC and their deregulations were more pronounced in advanced right-sided tumours and with the loss of Smad4 protein, suggesting their important contribution to cancer development and aggressiveness." (PMID 34867090, 2021). "Analysis of 55,308 cancers registered in a public database revealed a significant trend toward co-occurrence of mutations in KRAS and SMAD4 (p < 0.0001; see Section 4.4 for details), indicating a potential synergistic role of these mutations in cancer survival and progression." (PMID 35008475, 2021). "We identified and characterized over 3600 somatic mutations in 29 miRNA biogenesis genes and showed that some of the genes are overmutated in specific cancers and/or have recurrent hotspot mutations (e.g. SMAD4 in PAAD, COAD and READ; DICER1 in UCEC; PRKRA in OV and LIN28B in SKCM)." (PMID 33406242, 2021).
cancer (continued). "This may suggest a different role of SMAD4 in different cancers and different effects of these two types of mutations." (PMID 33406242, 2021). "Each individual subclonal mutation merits in-depth validation studies to explore its putative role in cancer biology since subclonal mutations could be neutral or clinically relevant, as has been shown here concerning SMAD4." (PMID 34749812, 2021). "Recently, it was reported that inhibition of the canonical TGF-β signaling due to loss of SMAD4 might be associated with cancer progression and drug resistance." (PMID 31952344, 2020). "Indeed, SMAD4 expression is down-regulated in several types of cancers causing the alteration of TGF-β pathway and resulting in tumorigenicity, angiogenesis, invasion and resistance to chemotherapy." (PMID 32244895, 2020). "Inactivating mutations in Smad4 are far more common in PDAC than in any other cancer type." (PMID 31480737, 2019). "Loss of Smad2 and Smad4 indicated death outcome in cancer patients." (PMID 31238579, 2019). "The mutation and down-regulation of SMAD4 contribute to many cancers progression." (PMID 30745456, 2019). "Indeed, GSEA indicated that the cancer hallmark “E2F_TARGETS” was enriched in SMAD4-deleted PDAC, accounting for the upregulation of cell cycle-related gene expression." (PMID 31569425, 2019). "The SMAD4 related enrichment of glycolytic enzymes in cancer derived Exo might underlie the reverse Warburg effect, the metabolic reprogramming involving stromal cells, such as cancer associated fibroblasts, cancer stem cells, and immune cells." (PMID 29156694, 2017). "Cancer associated SMAD4 mutations usually occur in this domain." (PMID 28267766, 2017). "Therefore, further studies including different types of cancer are needed to judge the association of clinical parameters with SMAD4 levels, and to reveal the associated mechanisms." (PMID 28199217, 2017). "Thus, specific binding inhibitor of PAK1-PUMA would induce cell death in Smad4-deficient or PAK1 activated cancers." (PMID 28423593, 2017). "However, for Stage II patients, high cytoplasmic IHC expression of SMAD4 was associated with an increased risk of cancer-specific mortality (log-rank, P = 0.047)." (PMID 28423626, 2017). "Actually, Smad4-deficient cancer cells are resistant to serum-deprivation-induced cell death." (PMID 28423593, 2017). "In addition, high cytoplasmic protein was associated with an increased risk of death for stage II patients, and, for stage III patients, low nuclear SMAD4 IHC expression was associated with an increased risk for cancer-specific mortality." (PMID 28423626, 2017). "We hypothesized that deleting Apc and Smad4 in this expanded stem-like population would cause aggressive carcinoma." (PMID 29113300, 2017). "We next investigated whether GSK3 inhibition could restore TGF-β signaling in a human cancer cell line carrying a point mutation in Smad4." (PMID 27308538, 2016). "Similarly, SMAD4 mutation was lost in cancer #8, and actually showed copy number gain, strongly suggesting loss of its sub-clone." (PMID 27045317, 2016). "Based on these results, our meta-analysis provided evidence that loss of Smad4 staining could act as an unfavorable biomarker in the prognosis of various cancers and should be used as a powerful tool in future clinical trials." (PMID 25333693, 2014). "Reportedly, cancer may hijack cytokine systems (e.g., SMAD4) via mutation to collect iron for proliferation." (PMID 25221514, 2014). "Thus, more studies that include more cancer types are needed to assess the association of clinical parameters and Smad4 and explore the appropriate mechanisms in the future." (PMID 25333693, 2014).